CRP (C-reactive protein)
Diseases named in the same sentence as CRP in open-access papers (continued):
Sharing a sentence is not in itself a finding about the gene and the disease.
COVID-19 (continued). "Our study confirmed that COVID-19 patients with comorbidities showed more pronounced leukopenia, lymphopenia, hypokalemia, hypoalbuminemia, coagulation disorders and higher levels of inflammatory indices ESR, CRP, IL-6, and IFN-γ." (PMID 33232277, 2020). "Inflammatory/infection markers (ESR, CRP, LDH, and PCT, but not IL-6), coagulation function tests (fibrinogen, PT, and D-dimer), and glucose were positively associated with the COVID-19 severity." (PMID 32746929, 2020). "IL-6-induced high levels of C-reactive protein (CRP) are typically more related to bacterial rather than to viral infections: in COVID-19 patients CRP values are very variable." (PMID 32849666, 2020). "This study aimed to investigate NLR with CRP to identify potential clinical predictors and analyze differences among severe and non-severe COVID-19 patients." (PMID 33244379, 2020). "D-dimer, fibrinogen, and high sensitive C reaction protein (hs-CRP) were higher in COVID-19 patients with pneumonia than in those without pneumonia." (PMID 32727465, 2020). "The presence or absence of comorbidities and CRP elevation were independent significant predictors of COVID-19 severity, and hypertension was found as the most common comorbidity in patients with severe disease." (PMID 32802219, 2020). "Elevated levels of CRP, TNF-, and IL-6 are involved in COVID-19 pathogenesis and may act as potential biomarkers for the management of the severity of the disease." (PMID 33244370, 2020). "The basal circulating IFN-γ levels were comparable with c-reactive protein in the discrimination of the occurrence of lung fibrosis among COVID-19 patients at discharge, unlike circulating IL-6 levels." (PMID 33133104, 2020). "C-reactive protein of the COVID-19-positive patients was elevated, but was not significant for differential diagnosis." (PMID 32948121, 2020). "In contrast, CRP showed an opposite tendency, indicating that ESR might be a practical reference indicator for dynamic monitoring of the virus activity in COVID-19 patients." (PMID 33282889, 2020). "Comparison of routine blood tests across the two timepoints demonstrates an acute, significant shift in the circulating levels of albumin, C-reactive protein, alanine amino-transferase (ALT), sodium, hemoglobin, lymphocyte, and platelet counts at COVID-19 diagnosis secondary to the acute illness." (PMID 32650523, 2020). "Regarding COVID-19 severity at admission of steroid-treated patients, the median PaO2/FiO2 was 236.5 (IQR: 142.5–303.7), the median value of lymphocytes was 860.0/uL (IQR: 635.0–1200.0) and C-reactive protein was 87.9 mg/L (IQR: 51.9–137.4)." (PMID 32878286, 2020). "The intrinsic cross-sectional nature of this study does not prove a relationship between VitD, CRP levels, cytokine storm, and severe COVID-19." (PMID 32876941, 2020). "The initial evaluation of potential hepatic damage in pediatric COVID-19 shall include AST/ALT, GGT, ALP, Ammonia, Bilirubin, lactate dehydrogenage (LDH), creatinine phosphokinase (CPK), d-dimer, C-reactive protein (CRP) and ferritin evaluations on Intensive Care Unit (ICU) admission." (PMID 33206767, 2020). "Leukopenia, lymphopenia, and elevated ESR and CRP were more common in recovered patients with severe COVID-19 than those who had non-severe cases." (PMID 33243228, 2020). "Short telomeres also possibly impact COVID-19 outcome through the modulation of cytokine production, as illustrated by our finding that TL correlated with NLR, which constitutes a prognostic factor in multiple diseases, and CRP." (PMID 33104521, 2020). "A recent retrospective study found a negative relation between serum 25(OH)D concentrations and CRP (a marker of inflammation and cytokine storm), in COVID-19 patients, which again indicates a protective role of vitamin D in reducing inflammation." (PMID 33396346, 2020). "Blood CRP and D-dimer have been shown to be significantly higher in severe COVID-19 patients when compared to non-severe cases." (PMID 33270751, 2020).
COVID-19 (continued). "Therefore, the levels of CRP, ESR, IL-6, ferritin, procalcitonin, and lactate dehydrogenase can serve as potential markers for the evaluation of COVID-19 prognosis." (PMID 33163160, 2020). "Patients with severe COVID-19 pulmonary involvement, as determined by the proposed CAD, presented higher lung weight and C-reactive protein at admission and more frequently required invasive ventilation and intensive care unit hospitalization with higher case fatality." (PMID 33344471, 2020). "Furthermore, the proportions of abnormal liver function tests (51.9% vs 22.2%, P < 0.0001) and elevated C-reactive protein level (90.2% vs 60.7%, P < 0.0001) were significantly higher in AOSD patients than in patients with COVID-19." (PMID 33552062, 2020). "Despite this, CRP was lower and their outcomes were no worse, reflecting the fact that they effectively acquired COVID-19 incidentally while in hospital rather than presenting due to severe infection." (PMID 32586323, 2020). "For all mild COVID-19 patients in Fangcang Shelter Hospital, some laboratory tests such as erythrocyte sedimentation rate and C-reactive protein were not performed." (PMID 33081700, 2020). "The percentage of detecting COVID-19 positive patient using RT-PCR is (98%), for suspected individuals using ROC and the best cutoff for lymphocytes percentage (≤21.8), neutrophils (≥67.7), ESR (≥37.5), CRP (≥6.2) and WBCs (≥7.15)." (PMID 33738019, 2020). "Additionally, they had significantly higher levels of COVID-19 specific laboratory test abnormalities including higher LDH, troponin T, procalcitonin, INR, Ferritin, CRP, AST, and absolute lymphocyte counts." (PMID 32997657, 2020). "COVID-19 subjects with critical illness have elevated CRP levels in comparison to their counterparts with a non-severe form of the disease." (PMID 33580031, 2020). "CK-MB, CRP, PCT, and LDH were elevated on frequent bases among pediatric COVID-19 patients." (PMID 33335873, 2020). "Even though the patient presented with a critical form of COVID-19, with laboratoryevidence of infection or inflammation, including elevated concentrations of CRP,ferritin, triglycerides and D-dimers, no other pathological microorganism wasidentified." (PMID 32876282, 2020). "When compared the COVID-19 group with the CAP and normal control groups, respectively, the mean value of CRP and SAA in the COVID-19 group (including mild, moderate and severe patients) had increased significantly (P < 0.01), whereas the mean values of C3, C4 and PA decreased (P < 0.01)." (PMID 32713370, 2020). "Our findings of elevated CRP, LDH, and ferritin in almost all of our patients at baseline indicate the severity of their presentation, and raise a consideration of these laboratory values as markers of prognosis in COVID-19." (PMID 32835113, 2020). "Laboratory values in the pneumonia control group (LDH, CRP, IL-6) were not significantly different compared to COVID-19 ARDS cases." (PMID 33123171, 2020). "Lymphocytopenia, increased D-dimer level, prolonged prothrombin time (PT), elevated liver enzymes, creatinine, cardiac markers, C-reactive protein (CRP), interleukin-6, and erythrocyte sedimentation rate (ESR) have been reported with variabilities among COVID-19 patients." (PMID 33282214, 2020). "Similar to previous studies among patients with influenza and bacterial pneumonia, elevated serum ferritin, lactate dehydrogenase, C-reactive protein (CRP), procalcitonin and erythrocyte sedimentation rate (ESR) predicted severe disease among patients with COVID-19." (PMID 32405783, 2020). "Likewise, other authors observed that, compared to younger patients, older COVID-19 patients had higher levels of AST, ALT, C-reactive protein and LDH, which illustrates the potential for more serious organ damage caused by SARS-CoV-2 infection in the elderly." (PMID 33141836, 2020).
COVID-19 (continued). "It showed that higher C-reactive protein, BUN, LDH and NLR on admission could significantly predict poor prognosis of COVID-19 infected elderly patients." (PMID 32651993, 2020). "COVID-19-related severe respiratory failure is characterized in part by increased numbers of neutrophils and lower numbers of lymphocytes (CD4, CD8, and CD19), as well as increased levels of serum IL-6 and C-reactive protein (CRP)." (PMID 33330130, 2020). "In a study of 77 COVID-19 patients, treatment with IFN-α2b significantly reduced the duration of detectable virus in the upper respiratory tract, and reduced the duration of elevated IL-6 and CRP levels." (PMID 32848776, 2020). "CRP levels were increased too, but statistically no significance was found between the groups of COVID-19 patients." (PMID 33505992, 2020). "Compared to COVID-19 patients without DM, the levels of C-reactive protein (CRP), myoglobin, alanine transaminase (ALT), and aspartate aminotransferase (AST) were significantly increased in DM patients." (PMID 33381599, 2020). "We demonstrate that COVID-19 patients who do not develop a bacterial infection present with high initial CRP levels and low-moderate PCT levels that gradually decrease over time." (PMID 33023606, 2020). "Recent research on cancer patients with COVID-19 had shown that non-surviving patients exhibit higher neutrophil counts and CRP levels." (PMID 33192519, 2020). "In an older, sedentary population (61–66 years), 6 months of both AE and RE resulted in increased circulating levels of anti-inflammatory IL-10 and reduced levels of IL-6, CRP, and TNF-α, which are all involved in the cytokine storm observed in severe cases of COVID-19." (PMID 33001410, 2020). "the results also showed that, lymphocyte percentages, neutrophils, CRP and ESR may be used as markers for COVID-19 helping prioritizing individuals for rRT-PCR test." (PMID 33738019, 2020). "Although CRP is a nonspecific marker, it becomes more specific to bioactivity of IL-6 and formation of a cytokine storm in patients with severe COVID-19." (PMID 32876941, 2020). "After seven days of treatment (T1), COVID-19 patients belonging to group A (not receiving canrenone) showed a significant improvement in [K+]plasma (4.6 mmol/L, p < 0.001), CRP (2.2 mg/dL), IL-6 (13 pg/mL), and ΔA-aO2 (135 mmHg)." (PMID 32933039, 2020). "Persistent lymphopenia, increased C-reactive protein, and persistently elevated LDH and α-HBDH may be signals of COVID-19 progression." (PMID 32656221, 2020). "The presence or absence of comorbidities and CRP elevation were independent significant predictors of COVID-19 severity." (PMID 32802219, 2020). "By using LASSO regression analysis, we further identified risk factors for the development of sepsis and found that changes in platelet counts, CRP, IL-6, BUN, and CK levels might be useful for predicting the incidence of viral sepsis among COVID-19 cases." (PMID 33178716, 2020). "Additionally, we also compared the peak levels of the clinical inflammation parameters C-reactive protein (CRP), IL-6, or ferritin with the expression of activation and inhibitory receptors on CD8+ and CD4+ T cells in COVID-19." (PMID 32983106, 2020). "This research aimed to investigate neutrophil‐to‐lymphocyte ratio (NLR) with C-reactive protein to identify potential clinical predictors and analyze differences among severe and non-severe COVID-19 patients." (PMID 33244379, 2020). "Consistent with this, higher levels of IL-6, CRP and fibrinogen were observed in COVID-19 patients with diabetes compared to those without." (PMID 33042029, 2020). "This study showed that patients with low HDL-C had higher level of CRP, which suggested that HDL-C may inhibit the inflammatory response and thus play a protective role in COVID-19 patients." (PMID 32892746, 2020). "As CRP is consistently elevated, this biomarker does not have predictive value for bacterial infections in the initial phase of COVID-19." (PMID 33023606, 2020).
COVID-19 (continued). "Although CRP is frequently reported as a prognostic marker, it did not provide additional prognostic value beyond illness severity in this sample of critically ill COVID-19 participants with multiple organ failure." (PMID 40868809, 2025). "However, it is possible that CRP levels do not fully capture the relevant immunopathological mechanisms induced by IL-6 receptor blockage in COVID-19." (PMID 40610416, 2025). "The clinical course of COVID-19 ranges from mild symptoms to severe complications, and common laboratory markers such as D-dimer, ferritin, interleukin-6 (IL-6), and C-reactive protein (CRP) often do not accurately predict which patients will develop severe disease." (PMID 40702494, 2025). "Patients with ILD showed no significant elevation in cytokines (IL-6, TNF-α, and IFN-γ), inflammatory biomarkers, C-reactive protein, ferritin, or D-dimer, indicating that patients with COVID-19 and ILD did not manifest additional hyperinflammation compared with the control individuals." (PMID 40573986, 2025). "One study pointed out that inflammatory markers such as CRP levels, serum ferritin and ESR in COVID-19 cases were positively correlated with glycated hemoglobin, while SaO2 was negatively correlated with glycated hemoglobin, therefore, low and elevated HbA1c levels may have a positive correlation." (PMID 39944495, 2025). "Compared to patients with COVID-19 who do not have diabetes, those with diabetes had heightened inflammatory responses (characterized by elevated neutrophils, serum ferritin, IL-6, CRP, and erythrocyte sedimentation rate) and suppressed immunity (marked by significantly reduced lymphocyte levels)." (PMID 41426569, 2025). "In this sense, a meta-analysis carried out in 2020 that evaluated 8719 COVID-19 patients with severe disease found that those patients hospitalized in the ICU had elevated levels of acute phase reagents, such as erythrocyte sedimentation rate, CRP, IL-6, and IL-10, among others." (PMID 40756075, 2025). "Crucially, individuals diagnosed with acute respiratory infections, including influenza, pneumonia (J09–J18), or COVID-19 (U07.1), did not exhibit substantially elevated biological age accelerations, despite typically showing high CRP values during acute illness." (PMID 41372266, 2025). "Nevertheless, for the COVID-19 patients, we did find clustering based on hospitalization status (ICU, ward, or discharge), showing that the main drivers of plasma proteomes (CRP, SAA1, and SAA2) can effectively function as clinical classifiers for disease severity." (PMID 40224277, 2025). "Thus, CRP, while non-specific, remains a robust surrogate for the cytokine-driven inflammatory burden in COVID-19." (PMID 41373577, 2025). "In this study of critically ill COVID-19 patients, plasma endostatin levels of 100–200 ng/mL at ICU admission were associated with AKI development on ICU day 1, RRT need, and 90-day mortality independent of age, sex, CRP, and creatinine." (PMID 40178654, 2025). "Strong correlations between sweat CRP levels and blood CRP levels were demonstrated in healthy subjects and patients with heart failure and acute or previous infections (e.g., COVID-19), suggesting that this technology can be used for non-invasive disease classification, monitoring, and management." (PMID 40293099, 2025). "Moreover, we did not report statistical significance in CRP levels with the severity of symptoms in a group of COVID-19-positive mothers." (PMID 40507109, 2025). "Additionally, colon cancer patients with COVID-19 have been reported to exhibit more severe symptoms, such as lymphopenia, elevated respiratory rates, and increased hypersensitive C-reactive protein levels, compared to COVID-19 patients without cancer." (PMID 40836050, 2025). "Secondly, factors associated with CRP elevation such as VTE were not collected; therefore, high CPR levels might not reflect a certain COVID-19 severity." (PMID 38450049, 2024).
COVID-19 (continued). "High IgA concentrations together with the most common non-respiratory and respiratory defining symptoms of COVID-19 severity (fever, dyspnea, cough, O2 saturation on admission, CRP and fibrinogen), obtained a predictive model with 93% reliability to detect the risk of COVID-19 pneumonia development." (PMID 38581072, 2024). "For instance, D-dimer and C-reactive protein levels were not collected, given that their roles as inflammatory and severity indicators in COVID-19 were unknown during the early stages of the pandemic." (PMID 38794194, 2024). "The study uses the clinical data of 500 COVID-19 patients from a designated hospital in Suzhou, China, and selects eight features, including age, sex, dyspnea, comorbidity, complication, lymphocytes (LYM), CRP, and lung injury score, as the most important predictors of COVID-19 severity." (PMID 38605874, 2024). "In adults who have survived COVID-19 and continue to experience persistent symptoms, there is a notable trend toward elevated levels of neutrophils, neutrophil-to-lymphocyte ratio (NLR), fibrinogen, D-dimer, ferritin, and C-reactive protein (CRP), coupled with decreased lymphocyte counts." (PMID 39204035, 2024). "CRP is a highly sensitive but nonspecific biomarker that indicates inflammation, tissue damage, and infection, and numerous studies have reported elevated CRP levels in patients with COVID-19." (PMID 39338474, 2024). "In addition, 16 age- and sex-matched non-COVID-19 clinical controls showed significantly lower levels in various laboratory parameters (e.g., CRP, ferritin, LDH) compared to non-survivors and convalescent COVID-19 cases as well." (PMID 38276214, 2024). "Moreover, CRP levels were not significantly increased in severe COVID-19 patients with HSV reactivation, whereas no data were found on procalcitonin levels." (PMID 39273246, 2024). "In individuals with non-severe COVID-19, a high CRP level may be a useful early marker for predicting the probability of disease development and can aid healthcare professionals in early patient identification and treatment." (PMID 39407172, 2024). "Other predictors of COVID-19 mortality include albumin, total bilirubin, Serum Glutamic Oxaloacetic Transaminase (SGOT), Serum Glutamic Pyruvic Transaminase (SGPT), nitrogen urea (p-ES), C-reactive protein (CRP), lactate dehydrogenase (LDH) and ferritin levels." (PMID 38216918, 2024). "However, the decrease in CRP levels should not be a variable that, alone, identifies COVID-19 patients suitable for weaning." (PMID 38597482, 2024). "Moreover, there is a statistically significant difference in mean CRP levels between those who survived COVID-19 and those who did not." (PMID 39408010, 2024). "CRP may not determine mortality in older COVID-19 patients, especially due to age-related rearrangements in immunity and cytokine production." (PMID 39124732, 2024). "However, the role of the inflammatory pathway in the clinical manifestations in the present study is uncertain, given that the concentrations of inflammatory markers, IL-6 and CRP, were similar in all individuals, irrespective of post-COVID-19 symptoms." (PMID 39056056, 2024). "Markedly higher levels of inflammatory indicators such as LDH and CRP have been reported in patients with severe COVID-19 compared to those with non-severe COVID-19, and this has been associated with higher risks of ARDS, ICU admission, and death, similar to the results of our study." (PMID 38504259, 2024). "Furthermore, the following laboratory findings showed abnormal mean values in terms of severity and mortality in COVID-19 patients: hemoglobin (HB) concentration, white blood cell (WBC) count, lymphocyte count (LC), C-reactive protein (CRP), creatinine (CREA), and uric acid (UA) levels." (PMID 39386928, 2024).